CA9 (carbonic anhydrase 9)
Diseases named in the same sentence as CA9 in open-access papers (continued):
Sharing a sentence is not in itself a finding about the gene and the disease.
tumor (continued). "Besides CA9, the tumor cells additionally expressed CD10, another marker of ccRCC, and PAX8, proving their renal epithelial origin." (PMID 35646693, 2022). "This suggests that the CA9-DATE treatment strategy can benefit from combinatorial tumor targeting strategies such as CAR T therapies or oncolytic viruses, including those that are engineered to secrete bifunctional T cell engagers, targeting additional GBM tumor associated antigens along with CA9." (PMID 35874663, 2022). "In CRC, CA9 is proved to promote tumor growth and necrosis in vivo." (PMID 35440019, 2022). "Moreover, an inhibitory effect on clonogenic survival was also shown for different tumor cells with reduced CA 9 expression or CA IX activity." (PMID 34445506, 2021). "Given that CA9 is a common downstream target of 887S and 887L, we sought to evaluate whether 887S and 887L regulated tumor cell progression via CA9." (PMID 34493285, 2021). "In addition, the percentages of cells expressing the hypoxia markers hypoxia-inducible factor 1-α (HIF1-α) and carbonic anhydrase-9 (CA-IX) in the residual tumor area after IRE-4d were 53% and 24%, respectively, compared with the control group, respectively." (PMID 35069599, 2021). "In ccRCC1, cluster 7 was identified as tumour cell type with highly expressed CA9 and NDUFA4L2." (PMID 34168986, 2021). "Tumour cells 2 had highly expressed CA9 and CP but lowly expressed NDUFA4L2." (PMID 34168986, 2021). "Thus, not only HIF1A, but also VEGFA, SLC2A1, and CA9 allow the tumor cells to survive in hypoxic environments and are well-established markers of cellular hypoxia." (PMID 33810575, 2021). "Consequently, the expression of CA9, NDUFA4L2, EGLN3, BHLHE41, VWF, IGFBP3, and ANGPTL4 is associated with ccRCC tumor progression and decreases at stage 4 after initial growth relative to normal tissues." (PMID 34046336, 2021). "Therefore, CA9 embedded in the cell membrane is an important part of the tumor pH regulation mechanism." (PMID 35155218, 2021). "Dual-targeting APE1/Ref-1 redox signaling and CA9 activity leads to dramatic enhancement of tumor cell killing in an ex vivo three-dimensional PDAC tumor coculture model even in the presence of the protective environment of the cancer-associated fibroblasts (CAFs)." (PMID 33436044, 2021). "Tumour cells were first identified according to the marker genes (CA9 and NDUFA4L2)." (PMID 34168986, 2021). "Using a panel of markers for tumor cells (CA9 and CD10), immune cells (CD45), endothelial cells (CD31), epithelia (CD326), and fibroblasts (PGFRα/β+), we found significant representation of viable cells, determined via propidium iodide exclusion, corresponding to all of these different cell types." (PMID 34884982, 2021). "Furthermore, the transcriptomics profiling revealed that tumor biomarkers changed as the cell cycle progressed and biomarkers of CA9, TK1 and EGFR were more abundantly expressed at early S stage." (PMID 34691667, 2021). "On the contrary, the tumor T-status, rate of distant metastasis, and the distribution of cell differentiation did not alter by the polymorphism of CA9." (PMID 32365566, 2020). "CA9 overexpression could prevent the accumulation of acidic metabolites in tumor cells at the expense of acidifying the extracellular tumor microenvironment." (PMID 32070368, 2020). "Importantly, immunohistochemical staining confirmed an inverse correlation between these two features: tumours with greater CA9 staining (a marker of hypoxic tumour cells) had lower prevalence of intratumoural T cells and vice versa." (PMID 33322840, 2020). "The in vivo fluorescent imaging and corresponding fluorescence intensity in tumor exhibited that the CA9 fluorescence intensity was substantially decreased after the implantation of oxygen‐generating depot, demonstrating the desirable tumor hypoxia‐alleviating effect." (PMID 33437566, 2020). "Consequently, the greatest reduction in tumour volume was achieved through silencing both ca9 and ca12 genes." (PMID 32570870, 2020).
tumor (continued). "This induces metallopeptidase activation with remodeling of the extracellular matrix and enhanced tumor-cell invasiveness, which may be one of the links between high tumor CA9 expression and poor prognosis." (PMID 32781554, 2020). "CA2 and CA4 occur in healthy human kidneys, whereas CA9 is only present in tumor tissue." (PMID 33276608, 2020). "Indeed, tumours with low CA9 expression and intense TIL presence in the tumour stroma defined a group of patients with optimal prognosis." (PMID 32066909, 2020). "This entire set of observations further indicated that the oxaliplatin-containing chemotherapy might have specifically targeted hypoxic, CA9-expressing tumor components." (PMID 32781554, 2020). "First, in order to assess whether a correlation between the expression of MCM2/CA9 genes and the growth rate of the tumor mass exists, we took advantage of a mouse model of subcutaneously injected NB tumor xenograft, using SKNBE2 cells." (PMID 33153038, 2020). "The strong overexpression of CA9 in our tumor samples confirmed the results of previous studies." (PMID 33276608, 2020). "The mRNA and protein expression of FABP5 was significantly higher in tumours from mice treated with bevacizumab than in mice treated with the control.Moreover, we examined the expression of CA9 (a hypoxia marker) and FABP5 in tumour sections taken from xenograft mouse tumours by IHC." (PMID 32550890, 2020). "The carbonic anhydrase 9 (CA9) is a zinc-containing glycoprotein protein that regulates cell proliferation and serves as a dominant factor in the disease course of several types of neoplasm." (PMID 32365566, 2020). "In conclusion, CA9 high expression correlates with poor prognosis and tumour grade in TSCC." (PMID 32299152, 2020). "CA9 expression correlated with clinical prognosis and tumour grade in TSCC." (PMID 32299152, 2020). "The tumor cells showed a continuous intensive staining of CA9." (PMID 33276608, 2020). "CA9 was detected in all primary tumor tissues and their exosomes." (PMID 33276608, 2020). "There was no direct association of CA9 with PD-L1 expression or the density of TILs in the tumour stroma, but CA9 was directly related to the extent of FOXP3+ TIL density (p = 0.008)." (PMID 32066909, 2020). "Indeed, we here show that, in vivo, the pharmacological inhibition of MCM2 and/or CA9 is efficacious to inhibit/block tumor growth, thus representing a novel promising therapeutic strategy." (PMID 33153038, 2020). "In addition to the role of CA9 in hypoxia, we found that CA9 had a significant correlation with TSCC tumour grade and cell differentiation." (PMID 32299152, 2020). "The frequency of detection of CA9 varies from 48% to 80% according to tumor site." (PMID 30863491, 2019). "This analysis showed the prognostic value of the CA9 mRNA or CAIX protein from the tumor tissue." (PMID 30654595, 2019). "Finally, we used a mouse model to investigate the localisation of ERO1α and CA9 in tumour xenografts using several cell lines." (PMID 31142270, 2019). "The CA9 mRNA and the miRNA-210 levels determined in the same tumor tissue were correlated." (PMID 30654595, 2019). "However, the staining of CA9 was very weak and localised to necrotic areas of the tumour, as previously reported." (PMID 31142270, 2019). "In addition, the upregulation of the tumor cell marker CA9 and osteopontin (OPN) expression exclusively in the LP derived cells underlines their neoplastic background." (PMID 31640774, 2019). "To validate these data, we have examined the expression of the tumor marker CA9 expression." (PMID 31640774, 2019). "Upon intradermal administration of the AdGMCAIX-transduced autologous DCs back into the patient, the DCs are expected to activate a cytotoxic T lymphocyte–mediated response against tumor cells positive for the CA9 antigen, and generate memory T cells, potentially resulting in decreased tumor growth." (PMID 31076951, 2019).
tumor (continued). "The aim of this study was to analyze the expression of carbonic anhydrase 9 in tumor tissue on mRNA (CA9) or the protein (CAIX) level and the level of secreted CAIX in the blood serum of OSCC patients to determine its potential as a prognostic biomarker and for future therapeutic stratification." (PMID 30654595, 2019). "As an optimal cut-off point, we defined 70% of the tumor samples (n = 51; CA9 mRNA level < 246, range: 0.63–246) with the lowest CA9 level as a low CA9 mRNA level, while the remaining 30% (n = 21) of the tumor samples were defined as overexpressing CA9 mRNA of ≥246.1 (range: 246.1–33779)." (PMID 30654595, 2019). "Based on these and other findings, it may be proposed that perturbation of CA9 glycosylation and/or caveolin-1 provides improved opportunities for enhanced targeting of the acidic tumor niche." (PMID 30767150, 2019). "These authors found a significantly higher CA9 mRNA level in the blood of two tumor patients." (PMID 30654595, 2019). "Furthermore, we found that those patients with a high tumor CA9 mRNA level (30% of all patients (n = 21)) had a significantly worse prognosis." (PMID 30654595, 2019). "Furthermore, we inspected its utility as a tumour hypoxia marker by comparing its expression to that of CA9 using in vitro cell cultures and an in vivo xenograft model." (PMID 31142270, 2019). "Along with low levels of CA9, this suggests that exponentially growing 231_HM.LNm5 tumours may experience less extreme hypoxia than the other tumour types and also that other factors may compensate for low VEGFA to promote angiogenesis." (PMID 29720474, 2018). "According to several studies, CA9 increases its expression with the increase in tumour stage, likely related to the degree of hypoxia, and could be used as a prognostic factor." (PMID 29745265, 2018). "We also provide evidence linking APE1/Ref-1 redox signaling directly to HIF-1 DNA binding in hypoxic cells and expand upon our previous finding that dual-targeting APE1/Ref-1 redox signaling and CA9 activity leads to enhanced tumor cell killing in a 3D PDAC tumor model." (PMID 30214007, 2018). "The authors found that the CA9 expression was greater in the initial stages of the tumour." (PMID 29745265, 2018). "In these cases, it is necessary to consider that these were patients with tumours and the presence of CA9 in CTCs (circulating tumour cells) was being identified in blood, as the dispersion of neoplastic cells from the primary tumour is a crucial point of the metastasis process." (PMID 29745265, 2018). "We therefore hypothesized that blocking CA9 production would increase tumor cells’ reliance on the available CA9 under hypoxic conditions, effectively sensitizing tumor cells to CA9 inhibition especially under hypoxia." (PMID 30214007, 2018). "The CA9 tumours present an adequate volume of viable tissue in which pHe is influenced by CAIX to allow accurate pHe measurements that can be compared with similar volumes of EV tissue which have much less CAIX expression." (PMID 30206370, 2018). "The relation of tumor stage and serum CA9 concentrations was investigated." (PMID 30011326, 2018). "This is important since activating mutations of the MAPK and phosphatidylinositol-3 kinase (PI3K) pathways, which occur in many tumor types, may consequently upregulate CA9 gene expression and influence intratumoral distribution of the CA IX protein." (PMID 29495652, 2018). "GGT1 and CA9 were expressed inside the primary tumor and in mLNs." (PMID 30542087, 2018). "Finally, as controls, we analyzed the mRNA expression of two hypoxia-inducible genes, VEGFA and CA9, and observed increased expression in the VHL-deficient tumor samples as expected." (PMID 29435132, 2018). "Hence, the entire extracellular viable volume of CA9 tumours was influenced by expression of CAIX, compared with the relatively small volume in EV tumours where CAIX was induced only at the hypoxic margin." (PMID 30206370, 2018).
tumor (continued). "Patient characteristics and tumor stage of CA9 immunohistochemistry in HCC specimen." (PMID 30011326, 2018). "Ongoing cell death and shedding may explain elevated CA9 levels in tumor patients, however the source in cirrhotic patients remains to be elucidated." (PMID 30011326, 2018). "Evaluation of clinical data may determine the usefulness of CA9 expression in tumor tissue as a biomarker for predicting the utility of SLC-0111." (PMID 30214007, 2018). "The miR-34a-CA9 axis is important in controlling tumor growth and metastasis of HCC cells." (PMID 28667334, 2017). "CA9 and Glut1 have their own function in tumor cells that could influence the behaviour of the cells expressing them." (PMID 27901496, 2017). "Potentially any HIF-1α responsive protein could act as a surrogate marker of tumour hypoxia and most attention has focused on carbonic anhydrase 9 (CAIX)." (PMID 28207045, 2017). "In addition, CA9 immunostaining in frozen tumour sections generally colocated with regions of binding of the hypoxic marker, pimonidazole, indicating the presence of hypoxic areas in xenograft tumours developed in the CAM assay." (PMID 28635961, 2017). "HIF-1α and CA9 expression was attenuated in the tumor exposed to DT." (PMID 28410215, 2017). "Furthermore, immunofluorescent staining of tumor cryosections with anti-CA9, a hypoxia marker, revealed that MMP-14 blockade reduced hypoxia in 4T1 tumors." (PMID 28938563, 2017). "Notably, we identified that CA9 was the top-ranked gene that was differentially expressed in iCl1/C1 tumors in comparison with other tumor subtypes (top)." (PMID 29018224, 2017). "With regard to the correlation of CA9, CD31, total CD68 and total CD20 expression with the clinicopathological parameters, patients younger than 65 years of age (median cut-off) had significantly lower percentages of tumor hypoxia and vice versa (low CA9 vs high: p < 0.001)." (PMID 27637082, 2016). "Indeed, from the n = 141 samples of the entire cohort, only 15 (10.6%) and 5 (3.5%) patients had a percentage of positive CA9 tumor surface area expression higher than 20% and 30%, respectively." (PMID 27637082, 2016). "A bioinformatics analysis revealed a strong correlation between TNC mRNA upregulation and expression of hypoxia-induced genes in both WT and R132H IDH1 patient GBMs, and expression of carbonic anhydrase 9 (CA9), a HIF1α-target gene, was reduced in R132H tumours." (PMID 27820599, 2016). "Hypoxia is also known to induce acidosis via increased acid load in the tumor microenvironment, a process that leads to upregulation of enzymes, such as carbonic anhydrase 9 (CA9), that can regulate extracellular pH allowing the tumor cells to thrive in the acidic microenvironment." (PMID 27588494, 2016). "The median tumor surface area positive for CA9 and CD31 was 7.8% and 8.1%, respectively." (PMID 27637082, 2016). "Likewise, mRNA expression of CA9, a marker for hypoxic exposure and tumor aggressiveness, was highly induced in response to low pO2." (PMID 27379206, 2016). "Of interest, HIF-1α gene expression was unchanged (HIF is rather expected to change on protein than on mRNA level), while hypoxia-responsive CA9 was highly increased in tumor samples, emphasizing the relevance of hypoxia-responsive factors in our CRC patient cohort." (PMID 27589845, 2016). "To that end, we measured CA9 protein in the serum of our patients with early T1a tumor stage and compared the results of these subjects with patient groups suffering from a more advanced disease, because a strong association between serum levels of CA9 with tumor stage has recently been reported." (PMID 26901863, 2016). "CA9 is a tumor hypoxia marker widely expressed in various types of human cancer." (PMID 27494883, 2016).
tumor (continued). "Calu-6 tumors showed extensive plasma membrane staining for CA9 in contiguous tumor cells bordering regions of necrosis, with 12.1% ± 0.9% of cells in Calu-6 tumors positively stained with CA9, demonstrating that Calu-6 tumors contain significant areas of hypoxia." (PMID 27020103, 2016). "Apoptosis was only activated in hypoxic tumor areas without associated expression of CA9, a protein expressed downstream of the primary hypoxia response characterized by HIF-1 stabilization." (PMID 26416246, 2015). "The biological effects of CA9 help to produce and maintain an alkaline pHi favorable for tumor growth, and participate in the generation of an increasingly acidic extracellular space, facilitating tumor progression." (PMID 25890268, 2015). "In addition, the near-infrared (NIR) fluorescent labeled sulfonamide derivatives were synthesized for imaging hypoxia-induced CA9 expressions in tumor cells in vitro, ex vivo, and in vivo." (PMID 26447758, 2015). "The serum CA9 was correlated with the tumor CA9 levels in different stages of CRC patients." (PMID 26447758, 2015). "Moreover, the CA9 expressions were also analyzed in tumor and non-tumor tissues from patients with high-level sCA9." (PMID 26447758, 2015). "The protein expression of CA9 was also higher in tumor tissue than in other organs." (PMID 26447758, 2015). "Negligible TH-302 activity in SU.86.86 may be attributed to a well-oxygenated tumor environment as evidence by low CA9 expression and reduced sensitivity to DNA cross-linking agents." (PMID 25635223, 2015). "Moreover, The M75 was another highly specific antibody for CA9, which recognized the extracellular proteoglycan-like domain of CA9 and widely used for western blotting, immunoprecipitation and IHC in human tumor tissues." (PMID 26447758, 2015). "Higher CA9 expressions were observed in tumor tissues than in non-tumor tissues." (PMID 26447758, 2015). "Previous studies indicated that sulfonamides could inhibit the activity of CA9 and resulted in pH regulation dysfunction in tumor cells." (PMID 26447758, 2015). "Therefore, we presume that the sulfonamide derivative decreases the CRC cell viability due to the insufficient activity and CA9 expression and thus they are unable to maintain the acidic tumor environment." (PMID 26447758, 2015). "In conclusion, the expression of hypoxic markers, including HIF-1α, CA9, GLUT1 and VEGF is common in patients with STS and is strongly associated with tumor progression, as indicated by the significant association of their expression with higher histological grade and advanced tumor stage." (PMID 25789026, 2015). "Tumours were harvested for hypoxia detection by CA9 immunohistochemistry." (PMID 26323213, 2015). "Furthermore, examining MDA-MB-231 xenografts for CA9 by immunostaining and NEAT1 by RNA-fluorescent in situ hybridization confirmed co-localization of NEAT1 with CA9 in regions distant from tumor blood vessels." (PMID 25417700, 2015). "Very few normal tissues, with the exception of stomach, express significant levels of CA9 so that positive staining for CA9 is considered an established marker of tumor hypoxia and a clinical indicator of aggressive cancers (for example, breast and bone) with poor prognosis." (PMID 25376898, 2014). "CA9-positive cells were observed more frequently in tumor specimens than in CNB specimens." (PMID 24893880, 2014). "Furthermore, ureido sulfonamide and glycosyl coumarin inhibitors of CA9 produced significant inhibition of primary tumor growth in human and mouse models of orthotopic breast cancer." (PMID 25376898, 2014). "In contrast, CA9, which is only expressed by tumor cells, might be more important at therapy initiation and possibly looses its importance during the course of treatment due to development of acquired resistance." (PMID 24086736, 2013). "Regions distal to tumor necrotic areas stained weakly for CA9 and HIGD1A." (PMID 23646141, 2013).